ALB (albumin)
Diseases named in the same sentence as ALB in open-access papers (continued):
Sharing a sentence is not in itself a finding about the gene and the disease.
tumor (continued). "We found that tumor size and number, BCLC stage, tumor capsule, ALB, AST, ALT, and AFP levels were related to the risk of all-cause mortality." (PMID 33505912, 2020). "The optimal cutoff points of age, tumor diameter, ALB, ALP, and APAR for predicting synchronous metastasis were 56 years, 3.6 cm, 39 g/L, 90 U/L, and 1.98, respectively, which were calculated by the ROC curves (Supplementary )." (PMID 32089687, 2020). "This particular uptake mechanism allows the albumin-based nanoparticles to bypass the drug efflux mechanisms in tumor cells." (PMID 35582218, 2020). "The optimal cutoff values of age, tumor diameter, ALB, ALP, and APAR for predicting recurrence were 54 years, 3.6 cm, 41 g/L, 79 U/L, and 1.95, respectively (Supplementary )." (PMID 32089687, 2020). "PEGylation, fusion to anti-albumin nanobodies or Fc domains, and multimerization have demonstrated longer serum half-lives; however, the trade-offs are lower tumor penetration and additional manufacturing costs." (PMID 32793488, 2020). "Inflammatory factors, such as C-reactive protein and serum albumin, are also reliable and sensitive indicators of the acute response of tumor cells to proper interventions." (PMID 32257553, 2020). "The stepwise multivariable regression identified albumin, Ln(bilirubin), macrovascular invasion, extrahepatic spread, largest tumour size and Ln(AFP) as statistically significant prognostic factors." (PMID 31579990, 2020). "An in vivo study directly showed that PDAC cells inside the tumor are able to internalize albumin through macropinocytosis and use albumin derived amino acids for further metabolic pathways, while adjacent normal cells do not have this ability." (PMID 32175281, 2020). "As a correlate to the indicated outcome measurements, molecular analysis of the albumin transport pathways related to nab-PTX transport into a tumour will be conducted in this study." (PMID 32532230, 2020). "Factors related to LNM in GC, including tumor size, grade, CT findings, Hb, platelet, albumin, fibrinogen, CEA, CA19-9, CA125, and CA72-4, were analyzed by random forest algorithm, and the importance of variables was ranked." (PMID 32984033, 2020). "The BBB was disrupted in more than 50% of tumor samples, so we excluded all peptides correlating with CSF albumin as candidate plasma leakage proteins from the analysis." (PMID 32610669, 2020). "Whereas, alanine and aspartate aminotransferase levels, albumin, HBV DNA level, PLR, AFP, tumor encapsulation, microvascular invasion, multiple HCC, tumor differentiation, and tumor size were associated with worse OS." (PMID 33178607, 2020). "Postoperative SCC-Ag level, albumin level, and detailed follow-up, including tumor recurrence and metastasis status, are also vital in analyzing the prognostic roles in patients with ESCC with stage T1-3N0M0." (PMID 32456707, 2020). "According to this study, hybrid gold–albumin nanoparticles should be considered promising photothermal agents, with excellent tumor ablation, good targetability, and lower toxicity, compared to nanoparticles alone." (PMID 32806755, 2020). "The patterns observed in both tumors are consistent with the development of local vascular disruptions and increases in permeability to albumin as parts of the tumor become less metabolically viable (hypoxic/necrotic) over time." (PMID 32960353, 2020). "In recent years, albumin has been intensively explored to construct nanocarrier for delivering drug and contrast agent to the tumor." (PMID 32183838, 2020). "As a novel inflammation-based prognostic indicator, the CRP to albumin ratio (CRP/Alb) has been shown to demonstrate excellent prognostic incentives in various tumor destinations." (PMID 32566124, 2020). "Preoperative serum albumin level and primary tumour site are independent prognostic factors of survival in patients treated for pathological femur fractures." (PMID 32245389, 2020).
tumor (continued). "The NEAT model evaluates number of active tumors (“N”), ECOG performance status (“E”), albumin (“A”), and primary tumor site (“T”)." (PMID 32592315, 2020). "Further improvement of tumor specificity is an important development direction for the albumin surface modification strategy." (PMID 33437580, 2020). "We also found that low Aldob expression was significantly correlated with α-fetoprotein (AFP), albumin level, and tumor encapsulation." (PMID 33275593, 2020). "This score includes parameters for liver function (1 point each for albumin < 36 g/dl or bilirubin > 17 μmol/l) and tumour burden (1 point each for alpha-fetoprotein (AFP) > 400 ng/ml and tumour size > 7 cm)." (PMID 32125515, 2020). "In this study, the advantages of nanotechnology and albumin with the ability of high tumor enrichment and the selective light initiation of the photosensitizer Temoporfin (mTHPC) were associated with a new delivery system for reliable tumor treatment." (PMID 33027891, 2020). "Perfluorocarbon is a safe O2 carrier that has been already demonstrated in clinic, and the encapsulation of perfluorocarbon with albumin enhanced its accumulation in the tumor site and rapidly released the oxygen that was physically dissolved." (PMID 33408716, 2020). "MDA-MB-231 tumors treated with low-dose albumin-bound paclitaxel showed a longitudinal decrease in LV-HC percent tumor volume at day 3 (p = 0.01)." (PMID 32599906, 2020). "Tumour number ≥ two (HR 1.54), alpha-fetoprotein > 400 μg/l (HR 1.14), serum albumin < 3.6 g/dl (HR 1.63) and total bilirubin > 0.9 mg/dl (HR 1.58) contributed significantly in Cox proportional hazards regression (each p < 0.05)." (PMID 32125515, 2020). "The reason for the reduced albumin concentrations in cancer cachexia seems to be tumor requirements." (PMID 32083092, 2020). "This optimized model incorporated fewer and less subjective parameters: the serum albumin, bilirubin and alpha‐foetoprotein, and macrovascular invasion, extrahepatic spread and largest tumour size on imaging." (PMID 31579990, 2020). "The criteria in this study included the up-to-seven criteria, which include tumor number and size, albumin concentration as a measure of liver function, and tumor marker (AFP) as malignant potential." (PMID 33112547, 2020). "The conjugate accumulates in tumor cells and is then cleaved by liposomes to doxorubicin and albumin." (PMID 32079289, 2020). "Mortality was significantly correlated with serum albumin, primary tumor size, serum AFP, treatment modality, treatment method and treatment line." (PMID 31232945, 2019). "The predictors of overall survival were tumor number (P = 0.019) and albumin levels (P = 0.045) for men, and only bilirubin levels (P = 0.008) for women." (PMID 30894157, 2019). "In our previous study, human serum albumin nanoparticles (HSA-NPs) were effectively delivered to the tumor site by sonoporation." (PMID 31022951, 2019). "Altogether, decreased serum albumin concentration provides prognostic information in advanced tumor stages in TETs." (PMID 31819103, 2019). "Once being internalized by tumor cells, the doxorubicin–albumin conjugate underwent a self-immolative reaction to release doxorubicin under the action of an abundant intracellular redox species." (PMID 31817418, 2019). "A concrete calculation formula for estimating survival probability was expressed as follows: S(t)=S0(t)exp(∑Xβ), ∑Xβ=0.005*age-0.269*gender-0.383*albumin+0.009*bilirubin+0.001*GGT+0.086* (tumor size)." (PMID 31777583, 2019). "The laboratory parameter C-reactive protein (CRP) increased significantly, whereas there was a significant decrease in leukocyte count, hemoglobin, albumin and cholinesterase as well as in the tumor marker CA 19.9." (PMID 31717736, 2019). "Peralta and his co-workers reported that paclitaxel-loaded gold nanorod encapsulated human serum albumin nanoparticle exhibited superior tumor growth inhibition." (PMID 30626093, 2019).
tumor (continued). "Patient age followed by three tumor markers and albumin level were the most important variables for HCC prediction." (PMID 31147560, 2019). "High expression of miR-196a or miR-196b was correlated with tumor size, tumor-node-metastasis stage, lymph node metastasis, albumin–bilirubin grade and poor 5-year survival." (PMID 30988277, 2019). "Albumin was instead diverted to and degraded in lysosomes, serving as a nutrition source for the tumor." (PMID 31354709, 2019). "The influence of age, location and size of tumors, nerve and vascular invasion, physical condition, and serology (serum albumin and tumor markers) on prognosis is neglected, limiting the application of the TNM staging system in clinical practice." (PMID 31729975, 2019). "The prognostic model was constructed based on four independent prognosticators: performance status, tumor stage, pre-treatment albumin level, and neutrophil-to-lymphocyte ratio." (PMID 30634387, 2019). "Tumor size, tumor number, alpha‐fetoprotein, prothrombin induced by vitamin K absence‐II, lymphocyte count, albumin, and presence of ascites were adopted to construct the prognostic nomogram from the derivation cohort." (PMID 31290618, 2019). "All four variables, (ECOG performance, tumor stage, albumin level, and NLR) were significant prognostic factors for OS in both univariate and multivariate analysis." (PMID 31385456, 2019). "The active internalization of albumin by tumor cells was recognized long before its interaction with FcRn was discovered." (PMID 31354709, 2019). "On the contrary, a recombinant protein of human serum albumin (HSA, 67 kDa) was localized up to three times more in a tumor over time when fused with a tumor targeting agent, amino-terminal fragment (ATF)." (PMID 31466360, 2019). "Following this platform, we developed cancer nano-theranostics by coupling biocompatible albumin backbone to CdTe QDs and mannose moieties to enhance tumor targeting and reduce QDs toxicity." (PMID 30660179, 2019). "Several studies have suggested tumors as sites of albumin catabolism, and the presence of putative albumin-binding proteins on tumor cell surfaces." (PMID 31060335, 2019). "Herein, a tumor microenvironment tailored multi-stage delivery system based on CYC loaded albumin nanoformulation and was designed for improved PDT therapy in breast cancer treatment." (PMID 31867309, 2019). "The analysis demonstrated that the preoperative FP score was significantly correlated with age, tumor size, fibrinogen level, pre-albumin level and white blood cell count." (PMID 31772657, 2019). "Following systemic administration, the phthalocyanines show improved tumor accumulation via transport by natural albumin." (PMID 31588226, 2019). "As a nanoparticle, nab-PTX is transported across the endothelial cell layer through EVs via biological albumin pathways and penetrates tumor tissue to increase the antitumor effect of PTX." (PMID 32064236, 2019). "In 1965, it was demonstrated that basic amino acid-rich histones and basic poly-amino acids can stimulate the internalization of albumin into tumor cells." (PMID 30850685, 2019). "For example, Martinez and collaborators developed alginate–cysteine/disulfide bond reduced albumin NPs that showed increased in vivo anti-tumor activity with increased drug concentration at the tumor site and undetectable levels of Tam in plasma." (PMID 31812165, 2019). "In this regard, albumin NPs (BSA NPs) are increasingly being used as drug delivery system for effective accumulation within tumour tissues through the enhanced permeability and retention (EPR) effect and albumin binding target proteins." (PMID 31694306, 2019). "Later on, the doxorubicin–albumin complex penetrated to the tumor core region and was ultra-smaller compared to the micro-size of engineered T lymphocytes." (PMID 31817418, 2019). "The doxorubicin–albumin complex was first cleaved under the more acidic tumor microenvironment (pH 6.5)." (PMID 31817418, 2019).
tumor (continued). "Among pre-palliative care factors, sex, age, tumor stage, Karnofsky performance status, neutrophil count, hemoglobin, lactate dehydrogenase, albumin, uric acid, and cystatin-C were identified as independent prognostic factors for OS." (PMID 31167668, 2019). "In contrast, we herein demonstrate a green tumor-targeting approach using in vivo albumin as a carrier for delivering molecular dye-based photosensitizers." (PMID 31588226, 2019). "In line with the GS model, the current study helped identify performance status, tumor stage, albumin, and NLR as independent prognostic factors that predict survival outcome." (PMID 31385456, 2019). "Univariate Cox models showed that resection margin status, tumour stage and pre-operative albumin levels were related to both time to death and time to recurrence." (PMID 30972486, 2019). "Our study identified ECOG PS, tumor stage, pre-treatment albumin level, and the NLR as being independent prognosticators for APC patients receiving GS." (PMID 30634387, 2019). "Age, tumor grade, primary tumor localization, lung metastases, trabectedin dose reduction, hemoglobin level, and albumin level also impacted PFS." (PMID 30917620, 2019). "A CRP level greater than 10 mg/L correlated with advanced tumor stage and reduced albumin and survival." (PMID 30941358, 2019). "The rationale of this study is to combine the merits of both albumin nanoparticles and quantum dots (QDs) in improved drug tumor accumulation and strong fluorescence imaging capability into one carrier." (PMID 30660179, 2019). "In the case of cancer, for example, it is well known that interstitial albumin is used as a source of biological energy by the tumor." (PMID 31195727, 2019). "Radiolabelled, colloidal albumin aggregates are currently used to detect sentinel lymph nodes in tumor diseases." (PMID 31195727, 2019). "The effects of tumour growth led to a decreased serum total protein (W < C and WL < L, p < 0.0001) and albumin (W < C, p = 0.0004; WL < L, p = 0.0002) content in the W and WL groups." (PMID 31200474, 2019). "In line with this it was also recently reported that albumin conjugated to the drug doxorubicin showed better tumor inhibition efficacy in pancreatic cancer when FcRn expression was reduced." (PMID 31354709, 2019). "Here, the authors report on an NIR-II fluorophore which binds with human serum albumin changing the equilibrium, increasing the photothermal efficiency, and demonstrate application of this for tumour ablation." (PMID 31101816, 2019). "The group of Dr. Yoon developed a theranostic tool able, in the presence of albumin, to exploit the avidity, of the tumor tissue for this protein." (PMID 31195727, 2019). "Their blood data including albumin and C-reactive protein for Glasgow Prognostic Score and cytokeratin 19 fragment 21-1 as a tumor marker were measured before starting treatment." (PMID 31038863, 2019). "Mannose-grafted strategy and QD-fluorescence capability were beneficial to deliver albumin nanocarriers to tumor tissues and then to release the anticancer drugs for killing cancer cells as well as enabling tumor imaging facility." (PMID 30660179, 2019). "The success of nab-paclitaxel has shown the potential of albumin as a drug carrier for tumor imaging and therapy." (PMID 31695779, 2019). "In this analysis, the factors predicting OS were the treatment arm, KPS, neutrophil-to-lymphocyte ratio, albumin level, sum of longest tumor diameters, and presence of liver metastasis." (PMID 31357748, 2019). "Normally, conventional albumin NPs can only passively deliver drugs to tumor sites through the enhanced permeability and retention (EPR) effect, which severely limits their delivery efficiency." (PMID 31623082, 2019). "ECOG PS, tumor stage, pre-treatment albumin level, and the neutrophil-to-lymphocyte ratio (NLR) were the most significant prognostic factors for OS in the multivariate analysis." (PMID 30634387, 2019).
tumor (continued). "Serum albumin is a marker of nutritional status and reportedly correlates with tumor necrosis, as pro-inflammatory cytokines reduce albumin synthesis." (PMID 31690275, 2019). "Strategies that significantly increase tumor retention can be envisaged such as continuous infusion, a process described for BiTEs or the addition of an anti-human serum albumin sdAb to confer a long serum half-life to the bsFab format." (PMID 31354732, 2019). "Based on our interesting findings, we further demonstrated a green and efficient delivery approach using the native albumin in vivo as the carrier to enhance the tumor-targeting ability of these phthalocyanines." (PMID 31588226, 2019). "In a similar way, the pH-responsive near-infrared croconine dye can induce self-assembly on serum albumin nanoparticles for real-time ratiometric (680 and 810 nm) optoacoustic tumor pH imaging." (PMID 30762162, 2019). "Although ex vivo studies showed that IgA1-albumin induced lower maximal tumor cell lysis, enhanced tumor cell killing was observed in vivo." (PMID 30984170, 2019). "The chemotherapeutic water soluble drug pemetrexed (PMT) was conjugated via tumor-cleavable bond to the albumin backbone for tumor site-specific release." (PMID 30660179, 2019). "The Abraxane® mode of action exploits different pathways characterized by tumor vasculature and cancer albumin transport." (PMID 31195727, 2019). "Multifunctional ANVs with targeting, and chemo- and photo-therapeutic properties were recently developed by modifying the albumin molecules with cyclic RGD (targeting tumor vasculature) in combination with Ce6." (PMID 31195727, 2019). "Albumin NPs have certain tumor-targeting properties that can improve in vivo drug distribution and reduce drug toxicity." (PMID 31623082, 2019). "Based on the results of univariate analyses, ECOG-PS, tumor type, prior treatment, serum ferritin, Hb, total bilirubin, γ-GT, albumin, WBC, and CRP significantly affected OS." (PMID 29879960, 2018). "Freshly dissociated tumor cells were frozen in 1 ml of human serum albumin (HSA) Vialebex® (LFB BIOMEDICAMENTS, Les Ullis, France) supplemented with 10% DMSO (Sigma Aldrich)." (PMID 29925435, 2018). "Some prognostic factors, including microvascular invasion, tumor-related factors, the Child–Pugh classification, and albumin-bilirubin (ALBI) score, have been reported as prognostic indicators in HCC patients who underwent hepatectomy." (PMID 30027102, 2018). "All three groups were similar with respect to age, gender, WBC, ALT, ALB, tumor differentiation, LNR, LN metastasis and chemotherapy treatment." (PMID 29580215, 2018). "ROC curve analyses showed that the optimal post-operative serum albumin cut-off level was 32 g/L (area under the curve [AUC] = 0.71) in predicting tumor recurrence and 31 g/L (AUC = 0.80) in predicting death." (PMID 30522461, 2018). "TPP-PS conjugate-albumin NPs showed preferential mitochondrial accumulation, mitochondrial membrane destabilization, apoptotic cell death, and enhanced antitumor efficacy in tumor-bearing nude mice." (PMID 30174604, 2018). "The patients with high neutrophil density in the central region of the tumour and the tumour invasive margin correlated with higher albumin-NLR and SIS score groups." (PMID 30419863, 2018). "On multivariate analysis, prognostic factors for an HIV-positive patient with NHL were previous ART therapy, advanced tumor stage and low level of albumin." (PMID 30083224, 2018). "Albumin can maintain stable plasma colloid osmotic pressure and enhance immune functions and has some anti-tumor effects." (PMID 29506546, 2018). "The following factors were identified as posing an increased risk for PC by the univariate analysis: tumor location, CA19.9, chemotherapy, albumin, WBC, and MPV." (PMID 29662100, 2018).